MMP12 (matrix metallopeptidase 12)
Diseases named in the same sentence as MMP12 in open-access papers (continued):
Sharing a sentence is not in itself a finding about the gene and the disease.
tumor (continued). "We found that the protein level of MMP2, MMP7, MMP9, MMP12, and MMP14 in the tumor tissue were basically higher than that in the normal tissue." (PMID 34804973, 2021). "The expression of MMP-12 will reduce the expression of VEGF (vascular endothelial growth factor) and inhibit tumor angiogenesis, thereby increasing the survival rate of patients with colorectal cancer." (PMID 34294834, 2021). "Depending on the MMP involved and the tissue site where a tumor is located, they can also have tumor-suppressive effects; an example of this is provided by MMP-8 and MMP-12, which are recognized as anti-tumor MMPs." (PMID 33419373, 2020). "When re-expressed, this miRNA functions as a tumor suppressor gene and inhibits CD133+ GSCs proliferation by targeting the NOTCH2 and matrix metalloproteinase-12 (MMP-12) mRNA expression." (PMID 33348804, 2020). "We aimed to measure ELN gene expression and its related MMP9, MMP12 and TIMP3 gene levels in tumor from CRC patients compared to adjacent non-tumor tissues and healthy controls in existing array datasets." (PMID 32171282, 2020). "Specific molecules which have the role of degrading proteins are called matrix metalloproteinases and are released in the tumor environment by tumor cells (MMP7, 14, 15, and 16), inflammatory cells (MMP12), and fibroblasts (MMP1, 2, 3, and 13)." (PMID 31934531, 2019). "Macrophages were reported to secrete matrix metallopeptidase 12 (MMP12) and stimulate TRAIL-dependent apoptosis in tumor cells." (PMID 31333662, 2019). "When the E:T ratio was 2:1, the expression of MMP9, MMP10 and MMP12 was also upregulated, indicating that the increase in MMP expression in the CAR-147 macrophages was related to tumour antigen stimulation." (PMID 31570753, 2019). "On the other hand, high levels of MMP-12 reduces CRC mortality as it can potentially inhibit angiogenesis by secreting angiostatin, a chemical that halts tumour progression and inhibits tumour neovascularisation." (PMID 31234411, 2019). "miR-107 functions as a tumor suppressor by reducing the expression of NOTCH2, CD133, nestin and Matrix Metallopeptidase 12 (MMP-12) in GSCs, impairing stem cell proliferation and invasion." (PMID 31450858, 2019). "Proteolytic enzymes such as ADAM28, MMP12 and MMP17, which can enhance extracellular invasion and expansion of tumor volume, were also upregulated in the irradiated SJGBM2-10gy cells." (PMID 30344926, 2018). "Further multivariate Cox regression analysis showed that TNM stage, tumor grade, TPX2 expression and MMP12 expression were independent prognostic factors (P < 0.05)." (PMID 30305064, 2018). "Then multivariate Cox proportional hazards regression analysis revealed that TNM stage, tumor grade, TPX2 expression and MMP12 expression were independent predictors (P < 0.05)." (PMID 30305064, 2018). "Among these differentially expressed genes, MMP1, MMP12, MMP13 and MMP28 were consistently reduced in hnRNP K-knockdown cells but elevated in tumor cells." (PMID 24885469, 2014). "The proteins in our classifier are related to the biology of tumor growth and function to sustain proliferation and activate invasion (MMP7 and MMP12), and respond to oxidative stress and deregulation of cellular energetics (CNDP1 and CA6)." (PMID 25114662, 2014). "To evaluate the effect of MMP12-dependent uPAR cleavage on tumor growth and on metastasis development in tumor bearing mice, we injected ECFC-MMP12 or ECFC-MOCK when tumor mass was evident in all the mice injected with A375 cells and MSC." (PMID 25003596, 2014). "It is generated through proteolytic cleavage of circulating plasminogen by a series of enzymes from the tumor environment, including the MMPssuch as MMP-2, MMP-7, MMP-9, and MMP-12." (PMID 25549350, 2014). "On the other hand, the mRNA levels of MMP1 and MMP12 were significantly elevated (14.2- and 56.3-fold, respectively; P < 0.05) in nine matched-pairs of NPC tumor and adjacent normal tissues." (PMID 24885469, 2014).
tumor (continued). "CD204(+) macrophages reportedly exhibit a tumor-promoting function in several tumors by secreting matrix metalloproteinase (MMP)-1, MMP-3, MMP-7, MMP-9, MMP-12, vascular endothelial growth factor (VEGF), and transforming growth factor (TGF)-β." (PMID 24376714, 2013). "A tumor protective role of a number of matrix degrading proteases, including MMP8 and MMP12, has been described." (PMID 18698413, 2008). "Using quantitative RT–PCR, overexpression of MMP1, MMP3, MMP7, MMP11, MMP12 and MMP13 in desmoid tumours was demonstrated." (PMID 15054469, 2004). "MMP12, a member of the matrix metalloproteinase (MMP) gene family secreted by macrophages, may serve as a marker of poor tumor prognosis." (PMID 40191203, 2025). "Depletion of resident macrophages reduces CXCL9 and MMP12 expression, alleviating renal injury without compromising anti‐tumor effects." (PMID 40810645, 2025). "While TAMs drive tumor progression through established pathways such as CSF1‐mediated recruitment or IL‐10‐induced immunosuppression, our discovery of the SRC‐1/STAT1/MMP12 axis revealed a distinct mechanism specific to PNI." (PMID 40985319, 2025). "Additionally, measurements of tumor migration distance within nerves revealed that the SRC‐1‐/‐ and MMP12 inhibitor groups had shorter migration distances than the controls." (PMID 40985319, 2025). "Additionally, MMP12 modulates the activity of growth factors and cytokines, such as VEGF and TGF-β, which play crucial roles in angiogenesis and inflammation within the tumor microenvironment." (PMID 39744560, 2025). "MMP12 might promote Foxp3+Treg infiltration in tumor tissue; TLR4 might obliquely attract Foxp3+Treg to the tumor location by interacting with TGF-β and macrophages." (PMID 38919615, 2024). "Immunoblotting experiments were performed to measure protein expression in tumor tissues, and the results showed that the expression of the autophagy-related protein LC3B was increased and that of P62 was decreased significantly in the MMP-12-knockdown group." (PMID 38511770, 2024). "Furthermore, our investigation revealed a notable upregulation of several matrix metalloproteinases (MMPs) in tumor-infiltrating macrophages, including MMP9, MMP12, MMP19, ADAM8, ADAM9, and ADAM17." (PMID 38254761, 2024). "Additionally, a bioinformatic study mirrored our results by demonstrating MMP1, MMP3, and MMP12 up-regulation in CRC, highlighting the potential universal relevance of these MMPs in tumor progression." (PMID 39596132, 2024). "Notably, HCC patients with high CSC levels exhibited an accumulation of SPP1+ macrophages (Macro_SPP1) expressing metalloproteinases (MMP9, MMP12, and MMP7) regulated by HIF1A, suggesting a hypoxic tumor region connecting Macro_SPP1 and CSC." (PMID 38521868, 2024). "As MMP12 stems from infiltrating immune cells rather than the tumor cells themselves, analyses performed on tissue biopsy material risk a biased selection of biomarkers produced by the tumour, while ignoring the surrounding microenvironment." (PMID 37391708, 2023). "From the perspective of data mining, this study suggests that MMP12, NFE2, and HOXC8 may be involved in tumor immune regulation and affect immunotherapy." (PMID 36650426, 2023). "SPP1+ macrophages from tumor tissues showed high expression of MMP9, MMP12, MMP14, and MMP19, which could contribute to the degradation of the basement membrane for the invasion of tumor cells." (PMID 38347955, 2023). "Notably, cluster Fib_4 cells exhibited tumor-promoting potential as they overexpressed CXCL12, MMP2, and MMP12." (PMID 37533434, 2023). "Matrix metalloproteinases (MMPs), including MMP12, dismantle various extracellular matrix (ECM) protein components, dissolving connective tissue between cells and within vascular layers, allowing tumor cells to escape their original location and initiate metastasis." (PMID 37889539, 2023).
tumor (continued). "Finally, we performed qPCR validation in clinical tissue samples and showed highly expressed POSTN, VISG4 in tumor samples, and highly expressed CXCL10, CXCL13, and MMP12 in normal samples." (PMID 36212488, 2022). "Besides, as part of the SASP, matrix metalloproteinases (MMPs) such as MMP10, MMP12, and MMP3 can lead to cleavage of NKG2D ligands on the surface of senescent tumor cells that allows them to evade NK cell surveillance." (PMID 36330438, 2022). "The second one is the lack of the exploration of mechanisms underpinning MMP12-medicated tumor immunity and the prognostic values of immune signatures." (PMID 35265129, 2022). "Moreover, macrophages secrete matrix metallopeptidase 12 (MMP12), which can mimic TRAIL and induce apoptosis in tumor cells." (PMID 34371753, 2021). "In this sense, we also acknowledge that potential dysregulation of inflammation-related genes included in our proposed molecular signature (e.g., IL1A, MCM2, MMP1, MMP12, and VEGFA) might be due to the inflammation favoring tumor maintenance and progression." (PMID 34638231, 2021). "Moreover, we have investigated the stromal score, immune score, and tumor purity of five subtypes, along with the estimate score of MMP1, MMP2, MMP9, MMP12, MMP13 in five subtypes of BRCA." (PMID 35069702, 2021). "We then assessed MMPs and TIMP3 expression in tumors and adjacent non-tumor colon tissue in CRC patients, MMP12 (P = 0.001), MMP9 (P = 0.0006) and TIMP3 (P = 0.0421) mRNA expression was significantly increased in tumors tissue compared to adjacent non-tumor tissue from CRC patients." (PMID 32171282, 2020). "These patients were characterized by higher tumor stage and overexpression of TPX2 and MMP12." (PMID 30305064, 2018). "For example, evidence for MMP12 as a BTNBC stromal marker was strengthened by the observation that its expression is absent in samples containing only tumor cells, but present in samples that typically contain a significant stromal cell component." (PMID 26980748, 2016). "Tumor invasion can be induced by macrophages through the production of enzymes and inhibitors that regulate the digestion of the ECM, as well as through the production of several MMPs including MMP-1, MMP-2, MMP-7, MMP-9, MMP-12 and MMP-14." (PMID 24578639, 2014). "Collectively, these results suggest an important role for MMP12 in inhibiting lung metastasis and indicate that MMP inhibitors could be designed to target tumour-promoting MMPs in order to inhibit tumour growth." (PMID 26316944, 2014). "Some authors showed that the effect of MMP12 is determined by cell-type expression: when expressed by host macrophages, it has a protective effect, while when expressed by tumor cells it did not." (PMID 25003596, 2014). "MMP-12 is involved in the breakdown of extracellular matrix and tissue remodeling, while MMP-13 is involved in the breakdown of extracellular matrix-collagen type II, which is important in tumor invasion and metastasis." (PMID 22815700, 2012). "It is interesting to note that two of the eight subjects studied had normal levels of MMP-12, whereas the other six had 15–50-fold elevation of MMP-12 in tumor tissue compared to non-tumor tissue." (PMID 22509397, 2012). "Besides overexpression of MMP7, a known β-catenin-dependent target gene in colon cancer, the results show an overexpression of MMP1, MMP3, MMP11, MMP12 and MMP13 in desmoid tumours compared to normal fibroblasts (fascia tissue)." (PMID 15054469, 2004). "Furthermore, the interaction between MMP12 macrophages and the CD86-CTLA4 ligand-receptor pair in T and B cells was significantly enhanced compared to that in normal samples; this interaction is critically important for tumor immunity." (PMID 40191203, 2025). "This study suggested that targeting resident macrophages or their downstream effectors, such as MMP12, could provide a strategy to mitigate renal toxicity without compromising systemic anti‐tumor immunity." (PMID 40810645, 2025).
tumor (continued). "However, despite the similar induction of SERPINA12 and MMP12 expression in the tumor, this does not correlate with survival." (PMID 41211185, 2025). "In addition, MMP12 expression was reduced in metastatic OSCC cancers compared to nonmetastatic OSCC tumours." (PMID 36902078, 2023). "Interestingly, both canonical and gene ontology analysis indicated enhanced MMP12 expression in HS5-PC3 cells, which is consistent with previous research outcomes implicating MMP12 with castration-resistant prostate cancer (CRPC) progression and tumour metastasis." (PMID 37372146, 2023). "However, the limitation of our preliminary work is that the relationship between tumor-derived IL-6 and macrophage MMP12 has not been well explored." (PMID 34863141, 2021). "We could see that about half MMPs are highly expressed in tumor tissues as compared with normal tissues, including MMP9, MMP10, MMP11, MMP12, MMP15, MMP25, MMP26 (all, P<0.05), while some other MMPs decreased in tumor tissues, including MMP2, MMP14, MMP16, MMP24, MMP28(all, P<0.05)." (PMID 32669958, 2020). "Therefore MMP12 seems to exhibit both protumorigenic as well as antitumorigenic properties probably due to the fact, if MMP 12 is derived rather from macrophages, stromal or tumor cells and the occurrence of functional single nucleotide polymorphism (SNPs)." (PMID 27431388, 2016). "Representative IHC images showed higher expression of MMP12 and MMP9 in the tumor stroma of LUAD compared with adjacent noncancerous lung tissues and tissues from patients taking atorvastatin." (PMID 37978381, 2023). "MMP12 gene expression is not changed, but MMP9 mRNA expression is increased in tumor from CRC patients compared to adjacent non-tumor tissues and controls." (PMID 32171282, 2020). "MMP7, MMP13, and MMP10 were significantly upregulated, while MMP12 and MMP9 were downregulated in metastatic tumour samples compared with nonmetastatic tumour samples." (PMID 31996191, 2020). "Thus significant fold changes appear restricted to only those samples containing recruited stroma (PDX mouse component, Finak_Stroma, and clinical tumor samples), suggesting that MMP12 expression is specific to BTNBC stroma, and absent in tumor cells." (PMID 26980748, 2016).
cancer (101 papers, 2005 to 2026). A tumor composed of atypical neoplastic, often pleomorphic cells that invade other tissues. "For example, MMP-7 has been linked to cancer cell migration and immune modulation, while MMP-12 is involved in inflammation and has roles in certain cancers." (PMID 40265458, 2025). "This analysis identified a core set of 24 genes that are downstream of MMP12 and implicated in at least one cancer-related category." (PMID 41465234, 2025). "A five-set Venn diagram was generated to map the intersections between the 113 downstream targets of MMP12 and the four cancer-linked gene sets." (PMID 41465234, 2025). "The MMP12 gene encodes for the matrix metalloproteinase 12, a proteolytic enzyme that can degrade the extracellular matrix and facilitate cancer cell invasion and metastasis." (PMID 38560573, 2024). "The associated genes with MMP12 were further reviewed, revealing significant associations with other genes that play active roles in cancer progression." (PMID 39124881, 2024). "MMP12 is a strong cancer progressor, and its significant association with other cancer progressor genes makes it a key gene to be considered a therapeutic target against cHL." (PMID 39124881, 2024). "Given its wide range of functions, MMP12 has been associated with many significant human diseases, including inflammatory diseases, different types of cancers and vascular diseases, and brain-related disorders." (PMID 36902078, 2023). "Previously, a high expression of MMP12 was found to be closely associated with the occurrence and progression of cancers at different sites, such as lung adenocarcinoma (LUAD), colorectal cancer, hepatocellular carcinoma, cervical cancer, and breast cancer." (PMID 37601247, 2023). "As SNP of MMP-12-82 A>G can influence the MMP-12 expression and enhance the cancer risk, the correlation between MMP-12 promoter gene polymorphism and the cancer risk has been extensively addressed in recent years." (PMID 34758846, 2021). "MMP-12 is primarily expressed by macrophages and has been implicated in various physiological and pathological processes, including tissue remodeling, inflammation, and cancer." (PMID 39739687, 2024). "Additionally, MMP-12 is also implicated in the pathogenesis of different types of cancer; however, the risk of cancer susceptibility remains controversial." (PMID 37513440, 2023). "Although dysregulation of MMP12 in cancer is common, its underlying molecular mechanisms remain unclear." (PMID 37601247, 2023). "Finally, the use of the mTOR inhibitor everolimus in cancer treatment has been linked to the development of PF through the upregulation of MMP-12 expression measured by RT-PCR." (PMID 35805895, 2022). "MMP12 may play a positive role in the process of glucose metabolism, lipid metabolism and cancer-induced cachectic muscle loss." (PMID 34863141, 2021). "And the up-regulation of MMP12 was associated with poor prognosis of cancer." (PMID 30305064, 2018). "MMP12, also known as macrophage metalloelastase is overexpressed in many cancer types, and high-level MMP12 expression has been associated with poor prognosis and increased risk of metastasis in cancer patients." (PMID 24885469, 2014). "Notably, two pathways (the T-cell receptor signaling pathway and the natural killer cell–mediated cytotoxicity) showed a direct association of MMP12 with immune cells, suggesting that MMP12 was likely to be involved in essential mechanisms of cancer through immune-related signaling pathways." (PMID 37601247, 2023). "Therefore, inhibiting MMP12 may represent a new potential target for the clinical treatment of cancer patients with weight loss." (PMID 34863141, 2021). "Furthermore, SFV infection of cancer cells downregulated several migration- and invasion-associated genes in macrophages (e.g., Mmp8, Mmp10 and Mmp12), particularly in the SFV/IFNγ group, suggesting that this approach may inhibit cancer cell dissemination and metastasis." (PMID 40547518, 2025).